BTK (Bruton tyrosine kinase)
Diseases named in the same sentence as BTK in open-access papers (continued):
Sharing a sentence is not in itself a finding about the gene and the disease.
chronic lymphocytic leukemia (continued). "Among B cell malignancies, those in which the most significant results were obtained by treatment with BTK inhibitors (BTKi) include chronic lymphocytic leukemia, mantle cell lymphoma, lymphoplasmacytic lymphoma, and diffuse large B cell lymphoma." (PMID 38542207, 2024). "Bruton Tyrosine Kinase (BTK) inhibitors find application in the therapeutic management of B-cell disorders, such as chronic lymphocytic leukemia, mantle cell lymphoma, Waldenström macroglobulinemia, and marginal zone lymphoma." (PMID 38542413, 2024). "Ibrutinib is an irreversible inhibitor of Bruton’s tyrosine kinase (BTK) that has revolutionized treatment of chronic lymphocytic leukemia (CLL) and is FDA approved for several hematologic indications." (PMID 39513363, 2024). "Novel agents, namely, venetoclax and Bruton tyrosine kinase inhibitors (BTKIs), are widely used in the frontline setting of chronic lymphocytic leukemia (CLL)." (PMID 38893198, 2024). "We conducted this first systematic review and meta-analysis to assess the competitive advantage of 2nd-generation Bruton tyrosine kinase inhibitors (BTKi) compared to 1st-generation BTKi in chronic lymphocytic leukemia (CLL)." (PMID 39050755, 2024). "BTK inhibitors (BTKis) have revolutionized the treatment of chronic lymphocytic leukemia (CLL) and other B cell malignancies." (PMID 39518015, 2024). "A notable example of TCIs is Ibrutinib, a first-in-class BTK inhibitor approved for the treatment of mantle cell lymphoma and chronic lymphocytic leukemia (CLL)." (PMID 37765103, 2023). "In chronic lymphocytic leukemia, cell proliferation is blocked by inhibiting BTK-mediated signal transduction." (PMID 37638060, 2023). "Ibrutinib, a BTK inhibitor developed to treat chronic lymphocytic leukemia and small lymphocytic lymphoma, has shown promise in treating aggressive glioblastoma by interacting with BMX." (PMID 37888725, 2023). "Chronic lymphocytic leukemia (CLL) is effectively treated with targeted therapies including Bruton tyrosine kinase inhibitors and BCL2 antagonists." (PMID 36376377, 2023). "Ibrutinib (also known as PCI-32765), discovered in 2007, is one of the first-generation BTK inhibitors approved for chronic lymphocytic leukemia (CLL)." (PMID 37848584, 2023). "Ibrutinib is a covalent inhibitor of BTK, in clinical use for treating lymphomas and chronic lymphocytic leukemia." (PMID 36682716, 2023). "Ibrutinib, is a potent inhibitor of BTK, which has been approved for the treatment of chronic lymphocytic leukemia." (PMID 37771591, 2023). "A 61-year-old man who had been treated for 4 years with the Bruton’s tyrosine-kinase (BTK) inhibitor ibrutinib as a first-line therapy for chronic lymphocytic leukemia (CLL) sought treatment for a painful rash." (PMID 36823687, 2023). "Bruton’s tyrosine kinase (BTK) is the target of the therapeutic agent, Ibrutinib, that treats chronic lymphocyte leukemia (CLL), mantle cell lymphoma (MCL) and other B cell malignancies." (PMID 37651403, 2023). "The inhibition of Bruton’s tyrosine kinase (BTK) has provided an array of therapeutic options for the effective treatment of chronic lymphocytic leukemia (CLL)." (PMID 37509398, 2023). "The efficacy of Bruton tyrosine kinase inhibitors (BTKi) remains suboptimal in chronic lymphocytic leukemia (CLL) treatment." (PMID 37328530, 2023). "Patients with chronic lymphocytic leukemia (CLL) or other B-cell cancers are treated with ibrutinib—an irreversible inhibitor of BTK." (PMID 36986673, 2023). "Ibrutinib is a once-daily oral Bruton tyrosine kinase (BTK) inhibitor that is approved as first-line treatment for patients with chronic lymphocytic leukemia (CLL)/small lymphocytic lymphoma (SLL) in the United States, Europe, and other countries." (PMID 36672456, 2023). "The Bruton tyrosine kinase inhibitor (BTKi) ibrutinib was shown to achieve high overall response rate and prolonged disease control in chronic lymphocytic leukemia (CLL)." (PMID 37380630, 2023).
chronic lymphocytic leukemia (continued). "The fifth place on the global sales list in 2019 was ibrutinib, which is a highly effective and selective small molecule BTK inhibitor for the treatment of chronic lymphocytic leukemia and small lymphocytic lymphoma." (PMID 36902773, 2023). "Ibrutinib, used to treat chronic lymphocytic leukemia and other cancers, is an inhibitor of Bruton’s tyrosine kinase (BTK)." (PMID 37112929, 2023). "The Bruton Tyrosin Kinase (BTK)-Inhibitor, Ibrutinib, is an established therapeutic agent for patients with B-cell malignancies such as relapsed or refractory chronic lymphocytic leukemia (CLL), mantle cell lymphoma (MCL), and Waldenström macroglobulinemia." (PMID 37655217, 2023). "The first-in-class inhibitor of exportin-1 (XPO1) selinexor is currently under clinical investigation in combination with the BTK inhibitor ibrutinib for patients with chronic lymphocytic leukaemia (CLL) or non-Hodgkin lymphoma." (PMID 37528310, 2023). "In recent years, ibrutinib, an oral BTK inhibitor, became a breakthrough therapy for hematological malignancies, such as chronic lymphocytic." (PMID 35456016, 2022). "It is a first-in-class BTK inhibitor approved for treating mantle cell lymphoma and chronic lymphocytic leukemia (CLL)." (PMID 36558928, 2022). "Ibrutinib, the first BTK inhibitor, regulates B cell receptor signalling and the development of B cells and has been approved for chronic lymphocytic leukaemia (CLL) and mantle cell lymphoma (MCL)." (PMID 36091028, 2022). "Bruton’s Tyrosine Kinase (BTK) is a well-known target expressed in certain B-cell malignancies including mantle cell lymphoma and chronic lymphocytic leukemia, and several BTK inhibitors are approved for human use." (PMID 36341428, 2022). "Bruton tyrosine kinase (BTK) inhibitors have improved chronic lymphocytic leukemia (CLL) outcomes and offer a chemotherapy-free option." (PMID 34974526, 2022). "Ibrutinib is the first covalent, irreversible BTK inhibitor approved in 2013 as a breakthrough therapy for chronic lymphocytic leukemia patients." (PMID 35628931, 2022). "Owing to the recent emergence of drug resistance to Bruton’s tyrosine kinase inhibitors (BTK) in chronic lymphocytic leukemia (CLL) treatment, it is crucial to identify alternative therapeutic targets." (PMID 35745653, 2022). "Inhibitors of BTK became a promising therapeutic modality in the treatment of e.g., chronic lymphocytic leukemia (CLL), Waldenstrom macroglobulinemia (WM), and mantle cell lymphoma (MCL)." (PMID 35954440, 2022). "Inhibitors that target BTK (BTKi) have emerged as breakthrough therapies for treating a variety of B-cell malignancies, such as chronic lymphocytic leukemia/small lymphocytic lymphoma, mantle cell lymphoma, and Waldenström’s macroglobulinemia." (PMID 36183831, 2022). "The availability of Bruton’s tyrosine kinase (BTK) inhibitor ibrutinib has undoubtedly reshaped the initial management of chronic lymphocytic leukemia (CLL)." (PMID 35159041, 2022). "BTK inhibitors (e.g. ibrutinib) have been developed to treat chronic lymphocytic leukemia (CLL) and mantle cell lymphoma (MCL) by blocking BCR signaling and regulating innate/adaptive immunity." (PMID 35410300, 2022). "Ibrutinib is a first-in-class oral irreversible inhibitor of BTK (Bruton’s tyrosine kinase) and has been demonstrated to be an effective treatment for chronic lymphocytic leukemia and other B-cell lymphomas." (PMID 36339006, 2022). "Targeting the B-cell receptor signaling pathway through BTK inhibition proved to be effective for the treatment of chronic lymphocytic leukemia (CLL) and other B-cell lymphomas." (PMID 34248972, 2021). "Ibrutinib, for example, which was the first BTK inhibitor to be used in clinical trials, has two approved indications, mantle cell lymphoma and chronic lymphocytic leukemia, and remains under evaluation for additional indications." (PMID 34447768, 2021).
chronic lymphocytic leukemia (continued). "Bruton tyrosine kinase (BTK) inhibitors have become an important therapy for untreated and previously treated patients with chronic lymphocytic leukemia (CLL)." (PMID 33567487, 2021). "Inhibitors of BTK have led to dramatic responses in patients with chronic lymphocytic leukemia (CLL) and mantle cell lymphoma." (PMID 33542970, 2021). "Genetic ablation or knockdown of BTK significantly reduces tumor growth in mouse model of chronic lymphocytic leukemia (CLL) or lymphoma cells." (PMID 34077419, 2021). "In contrast, lymphoma subtypes with activated BCR signaling are sensitive to BTK inhibitors (BTKis), and include chronic lymphocytic leukemia (CLL), mantle cell lymphoma (MCL), marginal zone lymphoma (MZL), and activated B cell (ABC) DLBCL." (PMID 34248972, 2021). "The approval of Bruton’s tyrosine kinase (BTK) inhibitors such as ibrutinib and acalabrutinib and the Bcl-2 inhibitor venetoclax have revolutionized the treatment of chronic lymphocytic leukemia (CLL)." (PMID 33809580, 2021). "BTK inhibitors including ibrutinib, zanubrutinib, and acalabrutinib show significant clinical effects in chronic lymphocytic leukemia (CLL), Waldenström macroglobulinemia (WM), and mantle cell lymphoma (MCL)." (PMID 35004280, 2021). "BTK inhibition has proven to be a highly successful therapeutic target in management of various B-cell malignancies such as chronic lymphocytic leukemia and mantle cell lymphoma." (PMID 34201396, 2021). "The effectiveness of BTK inhibition in pemphigus was first reported in a 51-year patient who suffered from chronic lymphocytic leukemia and developed paraneoplastic pemphigus (PNP)." (PMID 34447768, 2021). "Studies have verified BTK as an essential target for agents against chronic lymphocytic leukemia (CLL)." (PMID 34277564, 2021). "Several covalent BTK inhibitors have shown remarkable efficacy in the treatment of B cell malignancies, especially chronic lymphocytic leukemia." (PMID 33676527, 2021). "Using our own designed Bruton’s tyrosine kinase (BTK) PROTAC compounds, we show herein efficient BTK degradation in chronic lymphocytic leukemia (CLL) cells." (PMID 34055615, 2021). "Acalabrutinib is a next-generation, potent, highly selective, covalent small-molecule inhibitor of BTK approved in adults with previously treated mantle cell lymphoma and in patients with chronic lymphocytic leukemia or small lymphocytic lymphoma." (PMID 34080039, 2021). "Ligation of CD180 in chronic lymphocytic leukemia B cells leads to the activation of BTK/PI3K/AKT or p38 MAPK pathways and both pathways have been shown to affect the activity of NF-κB." (PMID 33809015, 2021). "Otherwise, ibrutinib, a Bruton’s tyrosine kinase (BTK) inhibitor, improved engraftment of CAR T cells, tumor clearance, and survival in human or xenografts models of BTK-resistant acute and chronic lymphocytic leukemia." (PMID 33919245, 2021). "Inhibitors of the BTK (Bruton’s tyrosine kinase) are used in various B-cell malignancies, including chronic lymphocytic leukemia and mantle cell lymphoma." (PMID 33793337, 2021). "The MyD88-independent pathways of CD180 signaling under pathologic conditions has only been investigated in chronic lymphocytic leukemia cells showing the activation of BTK/PI3K/AKT or p38 MAPK pathways." (PMID 33809015, 2021). "Ibrutinib is a Bruton’s tyrosine kinase (BTK) inhibitor approved by the FDA for the treatment of chronic lymphocytic leukemia (CLL)." (PMID 34794490, 2021). "Acalabrutinib is a Bruton’s tyrosine kinase (BTK) inhibitor approved for treatment of chronic lymphocytic leukemia and mantle cell lymphoma." (PMID 32607505, 2020). "A pathological BTK upregulation has been shown in B‐cell malignancies such as chronic lymphocytic leukaemia." (PMID 31736210, 2020).
chronic lymphocytic leukemia (continued). "The BTK inhibitor ibrutinib is well known as a treatment option in chronic lymphocytic leukemia and mantle cell lymphoma, in which ibrutinib silences the downstream pathways of ERK, PI3K, NF-κB and Akt, and induces apoptosis of malignant B cells." (PMID 32146518, 2020). "Ibrutinib, a pyrazolopyrimidine derivative, is a Bruton’s tyrosine kinase (BTK) inhibitor useful for the treatment of mantle cell lymphoma and chronic lymphocytic leukemia." (PMID 32645858, 2020). "Inhibition of BTK by LFM-A13 induced growth reduction in chronic lymphocytic leukaemias, diffuse large B-cell lymphomas of the activated B-cell type, and mantle cell lymphomas." (PMID 32912025, 2020). "Ibrutinib is a Bruton tyrosine kinase inhibitor approved for the treatment of chronic lymphocytic leukemia (CLL) in 2014." (PMID 32503582, 2020). "Targeted inhibition of Bruton’s Tyrosine Kinase (BTK) with ibrutinib and other agents has become important treatment options in chronic lymphocytic leukemia, Waldenström’s Macroglobulinemia, Mantle cell lymphoma, and non-GCB DLBCL." (PMID 32824276, 2020). "BTK upregulation has been demonstrated in various B cell malignancies such as chronic lymphocytic leukaemia and multiple myeloma; this has prompted the development of small molecule BTK inhibitors for the treatment of these diseases." (PMID 33298896, 2020). "The Bruton tyrosine kinase (BTK) inhibitor ibrutinib provides effective treatment for patients with chronic lymphocytic leukemia (CLL), despite extensive heterogeneity in this disease." (PMID 31996669, 2020). "Constitutive BTK activation is essential for proliferation of abnormal B-cells in several types of blood malignancies including chronic lymphocytic leukemia (CLL), mantle cell lymphoma, and lymphoplasmacytic lymphoma." (PMID 32283832, 2020). "Ibrutinib, zanubrutinib, and acalabrutinib are synthetic BTK inhibitors (BTKi) used for the treatment of some hematologic malignancies, like B cell lymphoma and chronic lymphocytic leukemia (CLL)." (PMID 33262793, 2020). "Chronic activation of the Bruton’s tyrosine kinase (BTK)-mediated B-cell receptor (BCR) signaling is a hallmark of many B-cell lymphoid malignancies, including chronic lymphocytic leukemia (CLL) and diffuse large B-cell lymphoma (DLBCL)." (PMID 31801949, 2019). "The Bruton's tyrosine kinase (BTK) inhibitor ibrutinib is effective in the treatment of human chronic lymphocytic leukaemia and mantle cell lymphoma." (PMID 31286638, 2019). "In chronic lymphocytic leukemia, selective inhibitors against BTK and PI3KCD are used for patients unsuitable or refractory to the rituximab-based chemotherapy regimen." (PMID 31856901, 2019). "Considering the critical role of BTK in several B-cell malignancies, a BTK-specific inhibitor, ibrutinib, is currently used to treat some types of lymphoma (such as mantle cell lymphoma) and chronic lymphocytic leukemia." (PMID 31238520, 2019). "BTK inhibitors (e.g. ibrutinib) are already being used in human disease for hematologic indications (chronic lymphocytic leukemia and small lymphocytic lymphoma), highlighting the real translational potential of this pathway." (PMID 29370834, 2018). "The importance of BTK in the pathogenesis of chronic lymphocytic leukemia, diffuse large B-cell lymphoma, and other mature B-cell malignancies is well established, while there is less information about the role of BTK in ALL." (PMID 30016959, 2018). "The introduction of the irreversible first-generation BTK inhibitor, ibrutinib, to clinical practice has changed outcomes for patients with chronic lymphocytic leukemia (CLL), mantle cell lymphoma (MCL), and Waldenström macroglobulinemia (WM)." (PMID 29690649, 2018). "BTK inhibition has showed its potency in clinics as well as in clinical trials for Small Lymphocytic Lymphoma, Chronic Lymphocytic Leukemia, Diffuse large B-cell Lymphoma, and Mantle Cell Lymphoma." (PMID 28915637, 2017).
chronic lymphocytic leukemia (continued). "Ibrutinib is a selective covalent inhibitor of BTK and has excellent clinical activity in patients with chronic lymphocytic leukemia and lymphoma." (PMID 28946903, 2017). "Ibrutinib is the first BTK-specific inhibitor and approved for the clinical treatment of mantle cell lymphoma and chronic lymphocytic leukemia." (PMID 28946903, 2017). "For example in a study with 85 CLL (chronic lymphocytic leukemia) patients treated with the Bruton's tyrosine kinase (BTK) inhibitor ibrutinib 7 patients developed Richter`s transformation, a more aggressive lymphoma form, during ibrutinib treatment." (PMID 28978042, 2017). "Ibrutinib, an oral inhibitor of Bruton tyrosine kinase (BTK), has shown strong activity in relapsing patients with Chronic Lymphocytic Leukemia (CLL) and MCL." (PMID 28791187, 2017). "The BTK inhibitor ibrutinib is used to treat chronic lymphocytic leukaemia, however some patients develop resistance to the drug." (PMID 27199251, 2016). "Ibrutinib (ibr), a first-in-class Bruton tyrosine kinase (BTK) inhibitor, has demonstrated high response rates in both relapsed/refractory and treatment naïve chronic lymphocytic leukemia (CLL)." (PMID 27626698, 2016). "The first-in-class Bruton’s tyrosine kinase (BTK) inhibitor, ibrutinib, has been in clinical use for the treatment of chronic lymphocytic leukemia, mantle cell lymphoma, and Waldenstrom’s macroglobulinemia." (PMID 26957112, 2016). "It has previously been shown that SDF1/CXCR4-induced migration is dependent on activation of downstream BTK in chronic lymphocytic leukaemia (CLL) and multiple myeloma." (PMID 25294819, 2014). "Ibrutinib is the first small-molecule Bruton tyrosine kinase inhibitor approved for treatment of chronic lymphocytic leukemia, initially for relapsed/refractory disease and patients with del 17p, and later also for frontline treatment irrespective of genetic features." (PMID 40723186, 2025). "BTK inhibitors, by targeting Bruton tyrosine kinase, disrupt B-cell receptor signaling to inhibit B-cell proliferation and survival and are widely used in B-cell malignancies such as Chronic lymphocytic leukemia/small lymphocytic lymphoma and MCL." (PMID 40642073, 2025). "Thus, the time-limited use of Thal-based regimens should be explored in the future, similar to the use of BTK inhibitors in the treatment of chronic lymphocytic leukemia." (PMID 40069155, 2025). "CLL and small lymphocytic lymphoma (SLL) are the disease in which BTK inhibitors have been more extensively employed, both in the relapsed and refractory setting and in treatment‐naïve patients, across the entire spectrum of cytogenetic and molecular risk features." (PMID 39887627, 2025). "Ibrutinib, an efficacious Bruton’s tyrosine kinase (BTK) inhibitor endorsed by the US Food and Drug Administration for treating chronic lymphocytic leukemia, mantle cell lymphoma, and so on, is linked to elevated risks of atrial fibrillation (AF) and hemorrhagic complications." (PMID 39469220, 2024). "Herein, we provide a detailed review, describing the clinical trials that led to the FDA approval of the BTK inhibitors for management of Chronic Lymphocytic Leukemia (CLL), Mantle Cell Lymphoma, Marginal Zone Lymphoma (MZL), Follicular Lymphoma (FL) and Waldenstrom Macroglobulinemia (WM)." (PMID 39456530, 2024). "The non-catalytic functions of BTK might also play an important role for treating B cell malignancies such as chronic lymphocytic leukemia for which BTK inhibitors such as ibrutinib are increasingly prescribed, even in first line now." (PMID 39120280, 2024).